SAA1 (serum amyloid A1)
Diseases named in the same sentence as SAA1 in open-access papers (continued):
Sharing a sentence is not in itself a finding about the gene and the disease.
glioma (11 papers, 2018 to 2025). A benign or malignant brain and spinal cord tumor that arises from glial cells (astrocytes, oligodendrocytes, ependymal cells). "The sensitivity and specificity of SAA1 to the glioma grades were positively associated with glioma grades III and IV, as indicated by a receiver operating characteristic (ROC) curve, but not with grade I or II." (PMID 29603594, 2018). "The level of SAA1 was associated with the glioma grade, disease severity, medication requirement, and GBM patient mortality, specially proneuronal type GBM patients." (PMID 29603594, 2018). "This suggests that SAA1 not only correlates with glioma grades but also highly associates with the clinical symptoms and disease severity of patients with GBM." (PMID 29603594, 2018). "Additional plasma and 52 brain tissues obtained from patients with gliomas were used to validate the association rate of serum amyloid A1 (SAA1) in different grades of gliomas and its distribution in tumors." (PMID 29603594, 2018). "In addition, we found that in glioma tissues from the TCGA database, SAA1 levels were associated with a range of anti-apoptotic genes (Bcl-xl, BFL1, MCL1, BIRC5, and Fas) and pro-apoptotic genes (Bim, Bid, CASP9 and Apaf1)." (PMID 33854635, 2021). "By contrast, we found that the gene expression levels of SAA1 in brain tumors were associated with glioma malignancy and patient mortality at threshold 25, and that high levels of SAA1 were specifically associated with the mortality of patients with the proneural type." (PMID 29603594, 2018). "SAA1 expression was statistically significant in GBM compared to the normal samples and other glioma subtypes and negatively associated with survival." (PMID 35756918, 2022). "Thereafter, expressions of SAA1 were successfully verified in an external database Chinese Glioma Genome Atlas (CGGA) and glioma cell lines (U87MG, and U251)." (PMID 35756918, 2022). "All the glioma samples were grouped into high- or low-expression groups after comparing the median SAA1 expression levels." (PMID 35756918, 2022). "Recent studies in glioma also proved that SAA1 knockdown inhibits the phosphorylation of serine/threonine protein kinase B (AKT), which regulates the production of apoptosis-related proteins, such as Bcl2 and Bax, resulting in GBM cell death." (PMID 35756918, 2022). "The protein level of SAA1 in glioma cell lines U87MG and U251were significantly upregulated compared to normal glial cells NHA." (PMID 35756918, 2022). "Specifically, SAA1 differed between GBM and other gliomas, indicating that SAA1 was the representative TME-related gene of GBM compared to other subtype gliomas." (PMID 35756918, 2022). "Univariate and multivariate independent prognostic analysis showed that PRLHR and SAA1 were the independent predictor of glioma (univariate and multivariate analysis P < 0.05)." (PMID 35800054, 2022). "Further analyses demonstrated that compared to different subtype gliomas, SAA1 expression was higher in normal samples only in GBM of grade 4 glioma." (PMID 35756918, 2022). "The expression of SAA1 in GBM is significantly higher than that of low-grade gliomas (logFC=2.06, p<0.0001)." (PMID 33854635, 2021). "Our study strongly suggested that SAA1 was a regulator of cells apoptosis and acted not only as a prognostic marker but also a novel biomarker of sensitivity of glioma to TMZ." (PMID 33854635, 2021). "Taken together, these results suggested that SAA1 was a novel biomarker in predicting TMZ response in glioma patients." (PMID 33854635, 2021). "We analyzed the effect of SAA1 expression on the survival time of glioma patients with different treatments by using public TCGA and CGGA datasets." (PMID 33854635, 2021). "Study 36 has found that the combination of SAA1 and integrin αvβ3 is involved in the occurrence and progression of glioma disease." (PMID 33854635, 2021).
glioma (continued). "Low SAA1 expression segregated glioma patients who were treated with Temozolomide (TMZ) or with high MGMT promoter methylation into survival groups in TCGA and CGGA dataset." (PMID 33854635, 2021). "Consistently, SAA1 has been reported as a molecular/metabolic signature that can help identify patients are at high risk of malignant GBM and promotes glioma cells migration and invasion through integrin aVb3." (PMID 30867991, 2019). "Both the plasma and tumor levels of SAA1 were positively correlated with the grade and severity of gliomas." (PMID 29603594, 2018). "In summary, our findings indicate that SAA1 expression levels in tumor cells are positively correlated with glioma grade, disease severity, and patient mortality." (PMID 29603594, 2018). "Together, these results suggest that SAA1‐mediated glioma cell migration and invasion require cooperation with the downstream molecules integrin αV and β3." (PMID 29603594, 2018). "Basic characteristics of glioma patients with IHC scores of high (≥2) and low (≤1) serum amyloid A1 (SAA1) expression." (PMID 29603594, 2018). "(2013) revealed SAA1 to have a dual role in glioma migration regulation, although the mechanism is unclear, and upregulated SAA1 levels in human glioblastomas were suggested to create a high‐inflammation microenvironment." (PMID 29603594, 2018). "The present study not only clarified the dual effects of SAA1 in different GBM cell lines but also identified the downstream key molecules of SAA1‐induced glioma cell migration." (PMID 29603594, 2018). "Overall, our results suggest that the plasma level of SAA1 is positively correlated with tumor SAA1 expression, and peripheral SAA1 levels can thus be considered an indicator of glioma malignancy." (PMID 29603594, 2018). "SAA1, as a paracrine agent, induces tumor cell migration and invasion, which can consequently escalate the malignant grade of gliomas." (PMID 29603594, 2018). "In the present study, we applied two shRNA targeting SAA1 to reduce the transcription of the SAA1 protein in U87 glioma cells, which successfully reduced the motility and invasiveness of glioma cells." (PMID 29603594, 2018). "The expression and distribution of SAA1 were determined by immunohistochemical (IHC) staining using an SAA1‐specific Ab; 52 brain tumor tissues including four different glioma grades were analyzed." (PMID 29603594, 2018). "Our results demonstrate that SAA1 contributes to both glioma and normal astrocyte migratory and invasive abilities through the pErk signaling pathway." (PMID 29603594, 2018). "Some other studies showed a similar expression pattern of SAA1 in glioma samples." (PMID 35756918, 2022). "Consequently, we identified SAA1 as a biomarker of glioma TME via integrated bioinformatic analysis and further validated the expression of SAA1 in multiple databases and GBM cell lines." (PMID 35756918, 2022). "Furthermore, the survival analysis showed that in all glioma patients, low SAA1 expression had prolonged survival compared to high expression." (PMID 35756918, 2022). "We used TCGA and CGGA datasets to analyze whether SAA1 expression affected survival of glioma patients who treated with different treatments." (PMID 33854635, 2021). "We found the expression level of SAA1 affected the apoptosis of glioma cells." (PMID 33854635, 2021). "SAA1 may regulate the proliferation and migration of endothelial cells induced by glioma by binding to integrin αvβ3, thereby promoting tumor angiogenesis." (PMID 33854635, 2021). "In the serum of patients with glioma, SAA1 levels are increased (p<0.01)." (PMID 33854635, 2021). "Serum levels of SAA1 were associated with the grades of gliomas but did not affect the clinical outcomes of patients with GBM." (PMID 30867991, 2019). "We could hypothesize that these genes might contribute to the malignance of glioma and SAA1 and TIMP-1 may be biomarkers in GBM." (PMID 30867991, 2019).
glioma (continued). "In addition to glioma cells, SAA1 induced the migration of normal astrocytes and has been shown to promote angiogenesis in nasopharyngeal carcinoma and GBM." (PMID 29603594, 2018). "A study suggested that A172 glioma cells respond to SAA1 differently." (PMID 29603594, 2018). "SAA1 was identified from MS analysis, and its level was revealed to be correlated with the disease grade, clinical severity, and survival rate of patients with gliomas." (PMID 29603594, 2018). "Microarray database analysis further validated the coefficient of SAA1 levels in gliomas." (PMID 29603594, 2018). "(2017) also found that serum levels of SAA1 were associated with the grades of gliomas but did not affect the clinical outcomes of patients with GBM." (PMID 29603594, 2018). "Medication and serum amyloid A1 (SAA1) IHC scores among different grades of glioma patients." (PMID 29603594, 2018). "SAA1 may was a novel biomarker in predicting TMZ response in glioma patients." (PMID 33854635, 2021). "Moreover, Gliomas with low SAA1 expression have increased sensitivity to Temozolomide (TMZ)." (PMID 33854635, 2021). "The expression levels of POSTN, CHI3L1, SAA1, and MMP9 were assessed in various glioma cell lines (U87, U251, U118, A172, T98G, SF295, LN229, and SF126) using qRT-PCR." (PMID 39574472, 2024). "Previous studies have extensively documented the dysregulation and oncogenic properties of POSTN, CHI3L1, SAA1, and MMP9 in various cancer types, including gliomas." (PMID 39574472, 2024). "Taken together, our evidence indicates that the predictive model constructed using POSTN, CHI3L1, SAA1 and MMP9 expression had significant prognostic value for patients with glioma." (PMID 39574472, 2024). "The genes POSTN, CHI3L1, SAA1, and MMP9 were screened to establish a predictive model, which exhibited a significant correlation with glioma prognosis and served as independent prognostic factors." (PMID 39574472, 2024). "To ensure accuracy, we compared the gene expressions of POSTN, CHI3L1, SAA1, and MMP9 in these glioma cells using the CCLE database and confirmed that the classification was consistent." (PMID 39574472, 2024). "In this study, we identified SAA1, a new biomarker related to the TME of GBM, for the prognosis of this malignant tumor and an indicator to distinguish between GBM and other gliomas." (PMID 35756918, 2022). "Based on univariate and multivariate cox regression analysis, we identified five genes, FABP5, VEGFA, SAA1, ADM, and PRLHR, for prognosis prediction in patients with glioma." (PMID 35800054, 2022). "ELISA detected the concentration of SAA1 protein in the serum of 7 healthy or traumatic brain injury (TBI) subjects and 11 glioma patients." (PMID 33854635, 2021). "SAA1 could be a distinctive gene between GBM and other subtype gliomas, and thus a novel biomarker for estimating the survival and TME status." (PMID 35756918, 2022). "Thus, by generating an artificial gradient of these ligands in the microfluidic device we have demonstrated that both SAA1 and to a lesser extent, RSPO3, can drive glioma tumor cell chemotactic invasion." (PMID 35619544, 2022). "Furthermore, Western blot analysis showed that SAA1 is upregulated in GBM, which was confirmed by the external validation in the Chinese Glioma Genome Atlas." (PMID 35756918, 2022). "Interestingly, SAA1 expression was significantly lower in normal samples, except in GBM and grade 4 gliomas." (PMID 35756918, 2022). "Additionally, a predictive model based on five HUB genes (FABP5, VEGFA, SAA1, ADM, and PRLHR) was constructed to predict OS in patients with gliomas." (PMID 35800054, 2022). "However, combined with clinical characteristics, we found that in different subtype gliomas, anaplastic astrocytoma (AA), and GBM, SAA1 expression is correlated with survival." (PMID 35756918, 2022). "SAA1 may be a distinguishing factor between GBM and other glioma subtypes and a new biomarker for determining the TME status and patients' survival." (PMID 35756918, 2022).
glioma (continued). "CXCL10, CCL13, SAA1, and CCL27 were more highly expressed in elderly, high‐grade, 1p19q non‐codel, IDH‐wildtype glioma patients, while SSTR5, CCL21, and HTR1A expressions were low in these malignant clinicopathological features of gliomas." (PMID 33503296, 2021). "The results indicate that patients with high SAA1 expression, regardless of low-grade gliomas or GBM, have a poor prognosis." (PMID 33854635, 2021). "In addition, we found several hub genes with worse OS and higher expression level in glioma patients, including VEGFA, NDC80, TIMP1, SAA1, CENPA, CENPF, and NCAPG and we firstly found relationship of SAA1, TIMP1, and molecular pathology in GBM." (PMID 30867991, 2019). "Moreover, our study revealed that the expression levels of four genes (POSTN, CHI3L1, SAA1, and MMP9) were significantly elevated in glioma samples obtained from patients who experienced recurrence within one year after TMZ treatment, along with an increased risk score." (PMID 39574472, 2024). "The predictive model constructed using four genes involved in macrophages and cancer cells, namely POSTN, CHI3L1, SAA1, and MMP9, holds promise in distinguishing high inflammation-hypoxia-immunosuppression microenvironment signatures and helps optimize trametinib selection for glioma treatment." (PMID 39574472, 2024). "Moreover, SAA1 inhibition reduced the expression of the metastasis‐related proteins MMP9 and integrin αVβ3 in both GBM cell lines and patients' GBM cultures; neutralizing the secreted form of SAA1 in medium successfully reduced glioma cell migration and invasion." (PMID 29603594, 2018).
rheumatoid arthritis (11 papers, 2013 to 2024). A chronic, systemic autoimmune disorder characterized by inflammation in the synovial membranes and articular surfaces. "Previous studies have shown that the SAA gene family has been identified as an important biomarker for rheumatoid arthritis, with SAA1 being associated with the acute phase of inflammation." (PMID 35126370, 2021).
colitis (10 papers, 2014 to 2024). Inflammation of the colon. "One study showed that mice concurrently deficient in Saa1, Saa2, and Saa3 had attenuated colitis as assessed by histology." (PMID 37396595, 2023). "SAA1/2 double-knockout mice showed higher stool consistency as well as lesser rectal bleeding and other histologic damage associated with colitis." (PMID 37164984, 2023). "First, Saa1/2−/− mice exhibit increased susceptibility to chemically-induced colitis in mice, suggesting that SAAs contribute to intestinal immunity." (PMID 25073702, 2014). "Then, 5 days after transfer, decreased numbers of TH17 cells in the mesenteric lymph nodes and TH1 and TH17 cells in the colonic lamina propria were found in SAA1/2/3 tri-deficient mice, and their colitis histologic features were also attenuated compared to controls." (PMID 37164984, 2023). "Intriguingly, our results enriched the involvement of RARβ in the regulation of SAA expression, suggesting that short‐term RARs‐pan‐antagonist treatment blocked RA‐induced downregulation of SAA1/2 with crosstalk to C/EBPA in colitis colonic epithelial cells." (PMID 37983567, 2023). "In conclusion, we identified that L. intestinalis increased colon RA metabolism, which relayed its signals by suppressing SAA1/2 production, and consequently restraining Th17 cells to alleviate experimental colitis." (PMID 37983567, 2023). "Lesser distal colonic infiltration of macrophages was found in SAA1/2 double-knockout mice with colitis than in wild-type ones." (PMID 37164984, 2023). "Although an experiment using SAA1/2 double-knockout mice with DSS-induced colitis had produced similar results, another animal study with the same model had come to an opposite conclusion as SAA helps killing Gram-negative bacteria." (PMID 37164984, 2023). "Another highly upregulated gene in the miR-146a−/− small intestine was serum amyloid a 1 (Saa1), an acute phase, inflammation-promoting gene that has antibacterial effects and is required for protection from colitis." (PMID 26456940, 2015). "Although receiving RA administration, AGN‐treated mice developed more severe colitis with more Th17 cell infiltration and higher epithelial expression of Saa1, Saa2, and Cebpa, suggesting that RA could regulate C/EBPA in colitis via RARs." (PMID 37983567, 2023). "Furthermore, in SAA1/2 double-knockout mice with DSS-induced colitis, significantly decreased hematocrit values and shortened colon were found compared to that of wild-type ones, convincing that SAA helps attenuate susceptibility of colitis." (PMID 37164984, 2023). "Similarly, mice that were deficient in Saa1 and Saa2 that had colitis-associated colon cancer showed attenuated weight loss, gut histological damage, and gut inflammation, findings that suggest that Saa1/2 may augment colitis severity." (PMID 37396595, 2023). "In a colitis mouse model, SAA1/SAA2 double knockout mice displayed increased weight loss, histological disease scores and TNF-α expression, suggesting that SAA1/SAA2 may provide protection at the intestinal epithelial barrier through its direct antibacterial properties." (PMID 32477346, 2020). "In contrast, SAA1 expression was inhibited by IL-10, but this result was not statistically significant, which is consistent with previous reports demonstrating that IL-10 is an anti-inflammatory cytokine that can suppress colitis." (PMID 35303008, 2022).
melanoma (10 papers, 2012 to 2025). A malignant, usually aggressive tumor composed of atypical, neoplastic melanocytes. "Additionally, SAA-1 could induce anti-inflammatory interleukin-10 (IL-10)-secreting neutrophils, which have been linked to the consequent promotion of melanoma progression." (PMID 22917173, 2012). "Another group demonstrated that iNKT cells blocked the function of IL-10-producing neutrophils induced by melanoma tumor cells via serum amyloid A1 (SAA-1)." (PMID 32231116, 2020). "On day 14, the melanoma mice had a dramatic increase (>600-fold) in SAA-1 mRNA as compared to controls, indicating robust inflammation." (PMID 24681760, 2014). "Indeed, αSMA‐positive CAFs in human lung and liver melanoma metastasis were positive for SAA1 protein." (PMID 39924882, 2025).
Hepatic steatosis (9 papers, 2022 to 2025). Steatosis is a term used to denote lipid accumulation within hepatocytes. "However, we cannot exclude the possibility that accumulated SAA1 in Surf4-deficient hepatocytes is involved in the development of the mild fatty liver." (PMID 39105051, 2024). "TXNDC5, as we hypothesized, was correlated with hepatic steatosis and redox control in the liver, showing an increased liver mass with a higher fat content linked to Saa1 and Saa2 expressions." (PMID 35327511, 2022). "This acute-phase response protein is known to trigger hepatic steatosis and intrahepatic inflammatory response by forming a SAA1/TLR4/NF-kappaB/SAA1 feedforward regulatory circuit, reported to facilitate MAFLD progression." (PMID 39595946, 2024). "SAA1 can increase hepatic steatosis, activate HSCs, and increase ECM deposition in the liver via the Toll-like receptor (TLR) pathways, and its levels are increased in the liver and blood of patients with MASLD." (PMID 39105051, 2024). "Saa1 establishes a regulatory circuit involving Saa1/TLR4/NF-κB/Saa1 feedback, which serves as a trigger for the development of liver steatosis and the intrahepatic inflammatory response." (PMID 38068762, 2023). "SAA1 triggered hepatic steatosis and regulated inflammatory response by forming a SAA1/TLR4/NF-κB feedforward, which leads to NAFLD progression." (PMID 37007016, 2023). "In previous reports, hepatic overexpression of SAA1 aggravated fatty liver inflammation by promoting intrahepatic platelet aggregation, while, recently, SAA1 was shown to exacerbate hepatic steatosis via the TLR4-mediated NF-κB signaling pathway." (PMID 36423130, 2022). "Furthermore, in a fatty liver mice model, the knockdown of hepatic Saa1 reduced inflammation and hepatic steatosis." (PMID 41373837, 2025).